PLEKHA7 (pleckstrin homology domain containing A7)
Diseases named in the same sentence as PLEKHA7 in open-access papers (continued):
Sharing a sentence is not in itself a finding about the gene and the disease.
cancer (10 papers, 2010 to 2023). A tumor composed of atypical neoplastic, often pleomorphic cells that invade other tissues. "Since E-cadherin is involved in epithelial morphogenesis, signaling, and tumor progression, we explored PLEKHA7 expression in cancer." (PMID 26270346, 2015). "Since the relative composition of these ECM components is altered during fibrotic conditions or cancer, we also examined the junctional localization of PLEKHA7 and RNAi components upon plating epithelial cells to combinations of laminin, fibronectin, collagen I, and collagen IV." (PMID 36497003, 2022). "PLEKHA7 has been proposed to regulate AJ stability through its ability to link the microtubule cytoskeleton to E-cadherin, and the E-cadherin/catenin/cytoskeleton complex is a crucial regulator of cancer invasion." (PMID 20808826, 2010). "Given the ability of PLEKHA7 to modulate pro- vs. anti-tumorigenic E-cadherin function, it would be interesting to evaluate whether PLEKHA7 can regulate E-cadherin behavior in these cancer types." (PMID 29996940, 2018). "Finally, we sought to explore whether the decreased or undetectable PLEKHA7 protein expression in specific carcinomas could be due to reduced or undetectable mRNA levels, by carrying out quantitative RT-PCR on frozen tumor samples." (PMID 26270346, 2015). "Thus, a question that should be addressed using cellular and animal model systems is whether AJ stabilization through PLEKHA7-dependent microtubule anchoring is important in cancer development and progression." (PMID 20808826, 2010). "Another non-mutually exclusive possibility is that PLEKHA7 alters the number of cancer stem cell (CSC)-like cells in the SUM149 spheres." (PMID 33525380, 2021).
tumor (7 papers, 2015 to 2023). "Specifically, in vitro and in vivo experimental results showed that PLEKHA7 was gradually lost during tumour progression to malignancy in GC and that PLEKHA7 deficiency exacerbated tumour invasion and metastasis." (PMID 36823376, 2023). "In conclusion, decreased PLEKHA7 expression was associated with a poor prognosis and distant tumour metastasis of GC cells." (PMID 36823376, 2023). "In IBC, we have observed the selective disruption of PLEKHA7 in patient tumor samples, with PLEKHA7 loss being twice as common as cytoplasmic mislocalization." (PMID 33525380, 2021). "To reiterate, the loss or mislocalization of PLEKHA7 from the apical AJ in the context of functional basolateral cadherin–catenin complexes is expected to promote tumor properties." (PMID 33525380, 2021). "There is also a correlation between the loss of junctional localization of PLEKHA7 and of RNAi in tumor tissues and cell lines." (PMID 32272708, 2020). "We define in EOCs E-cadherin as a tumor enhancer that positively contributes to EGFR-promoting growth signaling due to loss of PLEKHA7 expression." (PMID 29996940, 2018). "The results of this and previous studies have shown the loss of PLEKHA7 expression in tumour tissues and elucidated the roles that PLEKHA7 plays in regulating tumourigenesis and metastatic miRNA levels, implicating PLEKHA7 in critical regulatory tumour invasion and metastasis mechanisms." (PMID 36823376, 2023). "Notably, by the end of our eight week study, we also observed that the majority of PLEKHA7-expressing tumors had bypassed PLEKHA7 tumor-suppression by losing PLEKHA7 or causing a cytoplasmic localization." (PMID 33525380, 2021). "Since PLEKHA7 is implicated in the stabilization of E-cadherin complex, and the expression and activities of both E-cadherin and the PLEKHA7-interacting protein p120ctn are linked to tumor formation and metastasis, we sought to explore if and how PLEKHA7 expression is altered in epithelial cancer." (PMID 26270346, 2015). "Therefore, investigations of the molecular mechanism of PLEKHA7 loss in tumours may be important for gaining a comprehensive understanding of tumour invasion and metastasis." (PMID 36823376, 2023). "The loss of PLEKHA7 expression disrupts the interaction of the microprocessor complex at ZA junctions, resulting in a decreased expression of tumour-suppressive miRNAs and an increased expression of certain miRNAs and genes related to carcinogenesis, tumour growth and/or migration." (PMID 36823376, 2023). "Therefore, since PLEKHA7 interacts with p120ctn, the loss of PLEKHA7 might contribute to tumor invasiveness, by altering the stability and signaling output of p120ctn." (PMID 26270346, 2015). "Then, an animal metastatic model experiment was performed to investigate the effects of hTERT and PLEKHA7 expression on GC tumour migration." (PMID 36823376, 2023). "For each morphological pattern, the average PLEKHA7 staining pattern across all tumor samples was calculated and categorized based on localization (apical, lost, cytoplasmic, or basal)." (PMID 33525380, 2021). "In orthotopic xenograft models, re-expression of PLEKHA7 slowed tumor growth, leading to decreased tumor volume." (PMID 33525380, 2021). "Re-expressing PLEKHA7 suppressed proliferation, anchorage independent growth, spheroid viability, and tumor growth in vivo." (PMID 33525380, 2021). "We cannot exclude the possibility that other mechanisms contribute to the tumor suppressive function of PLEKHA7 in IBC, including inhibiting p120 signaling, or suppressing E-cadherin/Epidermal growth factor receptor (EGFR) signaling." (PMID 33525380, 2021). "Our in vitro and IHC data indicated that PLEKHA7 acts as a tumor suppressor and is frequently misregulated in IBC." (PMID 33525380, 2021). "It is notable that PLEKHA7 must properly localize to the apical AJs to maintain its tumor suppressing function." (PMID 33525380, 2021).
tumor (continued). "This function of PLEKHA7 suppressed expression of pro-tumor promoting proteins, including Cyclin D1, Snail, and c-Myc, and inhibited AIG." (PMID 33525380, 2021). "By recruiting these complexes, PLEKHA7 regulates the processing and activity of a number of tumor-suppressing miRNAs, such as miR-30b, miR-24, miR-200c, and miR-203a." (PMID 32272708, 2020). "Together, these results are in agreement with our previous findings and further support a tumor suppressing role for PLEKHA7 in the colonic epithelium, through recruitment and regulation of the RNAi machinery." (PMID 32272708, 2020). "Knockdown of PLEKHA7 disrupted apical localization of E-cadherin and p120, and processing of tumor-suppressive microRNAs was misregulated." (PMID 26901232, 2016). "Furthermore, PLEKHA7 is gradually lost in certain tumours during tumour progression, suggesting that PLEKHA7 deficiency is a common mechanism of tumour development in these tumours." (PMID 36823376, 2023). "However, the molecular mechanisms regulating PLEKHA7 in tumour progression to malignancy are unclear." (PMID 36823376, 2023). "In contrast, the PLEKHA7 mRNA and protein levels were decreased in the hTERT-overexpressing, but not the p65-overexpressing, tumour cells compared with those in the control-overexpressing tumour cells." (PMID 36823376, 2023). "Combined with our prior studies showing that apical junctional localization of the PLEKHA7-RNAi complex is critical for regulating tumor-suppressing miRNAs, this work points to a yet unstudied mechanism that could contribute to epithelial cell transformation." (PMID 36497003, 2022). "This suggests the existence of selective pressure in tumor cells to lose apical PLEKHA7 expression." (PMID 33525380, 2021). "Next, we tested whether restoring PLEKHA7 expression in SUM149 cells would decrease tumor formation or growth in an animal model." (PMID 33525380, 2021). "Re-expression of PLEKHA7 restores apical AJs and suppresses tumor growth in vitro and in vivo." (PMID 33525380, 2021). "Altogether, our data is consistent with an important tumor suppressor function for PLEKHA7 in IBC." (PMID 33525380, 2021). "We hypothesize that the tumor suppressive effects observed with PLEKHA7 expression in SUM149 xenografts occurred early in tumor formation." (PMID 33525380, 2021). "Consistent with the hypothesis that PLEKHA7 acts as a tumor suppressor that is commonly lost in IBC, its re-expression in an IBC cell line significantly inhibited cell growth, both in 2D and particularly in 3D culture." (PMID 33525380, 2021). "Our investigation to understand how the adherens junctions may be acting as a tumor suppressor led to the revelation that PLEKHA7 recruits numerous RNA-binding proteins, including the main complexes of the RNA interference (RNAi) machinery." (PMID 32272708, 2020). "Hence, the biological impact of E-cadherin/EGFR complex at the junctions in relation with PLEKHA7 await further investigations in tumor cells others than EOCs." (PMID 29996940, 2018). "Whether a TJ protein associates with PLEKHA7 may determine whether it favors MET or EMT and thus its effect in a particular tumor cell." (PMID 26901232, 2016). "We have previously shown that PLEKHA7 depletion promotes pro-tumorigenic transformation of Caco2 cells and results in the disruption of junctional localization of RNAi complexes and downregulation of tumor-suppressing miRNAs, although E-cadherin-mediated cell-cell adhesion is still present." (PMID 32272708, 2020). "In solid areas, PLEKHA7 was lost in 56.4%, cytoplasmic in 26.4%, and localized to the basal membrane in 24.1% across all IBC tumor samples." (PMID 33525380, 2021). "In support, our data showed that restoring apical complex activity, via PLEKHA7, is sufficient to suppress IBC tumor growth in vitro and in vivo." (PMID 33525380, 2021).
tumor (continued). "We assessed for the first time in EOC cells that PLEKHA7 induces changes in the asset of E-cadherin-containing cell-cell contacts thus inhibiting E-cadherin/EGFR crosstalk and leading to a less aggressive tumor phenotype." (PMID 29996940, 2018). "The RT‒qPCR and western blot experiments demonstrated that the PLEKHA7 mRNA and protein levels were increased in the hTERT-knockdown, but not the p65-knockdown, tumour cells compared with those in the control-knockdown tumour cells." (PMID 36823376, 2023). "We found that PLEKHA7 expression is largely not apical in IBC tumors, indicating a loss of the tumor-suppressing function in this disease." (PMID 33525380, 2021). "Importantly, PLEKHA7 re-expression significantly suppresses anchorage-independent growth of HCT116 cells in vitro, in a soft agar assay, and tumor growth of these cells in a xenograft mouse model, in vivo." (PMID 32272708, 2020). "We did not test the mechanism by which PLEKHA7 executes these tumor-suppressor roles in IBC." (PMID 33525380, 2021).
adenocarcinoma (1 paper, 2024). A common cancer characterized by the presence of malignant glandular cells. "Parallel to that, 5 proteins were expressed lower in SOL adenocarcinomas and the low expression of which was correlated with poor OS, including PIGR, CHDH, NAPSA, PLEKHA7 and SELENBP1." (PMID 38182978, 2024).
PLEKHA7 also shares sentences with these, for which no sentence is quoted: primary angle-closure glaucoma (3 papers); atherosclerosis (1); colon adenocarcinoma (1); COVID-19 (1); essential hypertension (1); invasive lobular carcinoma (1); open-angle glaucoma (1); perinatal depression (1); pneumonia (1); prostate adenocarcinoma (1); renal carcinoma (1); skin infection (1); stomach adenocarcinoma (1).